NLRP1 (NLR family pyrin domain containing 1)
Diseases named in the same sentence as NLRP1 in open-access papers (continued):
Sharing a sentence is not in itself a finding about the gene and the disease.
ischemic stroke (continued). "As neuronal pyroptosis might be mediated by the activation of NLRP1 and NLRP3 inflammasomes in the course of ischemic stroke, western blot was performed to explore whether EE inhibited pyroptosis by suppressing the activities of NLRP1/NLRP3 inflammasomes." (PMID 34646128, 2021). "Circ_NLRP1 levels showed upregulation in vivo and in vitro models of ischemic stroke." (PMID 34227902, 2021). "As the first identified inflammasome in cerebral ischemic injury, NLRP1 inflammasome could activate precursor caspase-1 to produce both mature IL-1β and IL-18 to mediate neurocytes death after ischemic stroke." (PMID 31416289, 2019). "In our work, circ_NLRP1 was identified to play a potential regulatory role during the pathophysiological process of ischemic stroke, as demonstrated by our data that showed the initiation of cell apoptosis could be evoked by increased circ_NLRP1 under OGD treatment or NLRP3 mediation." (PMID 34227902, 2021). "Following ischemic stroke (IS), the NLRP3 or NLRP1 protein forms a multi-protein complex known as the NLRP3 or NLRP1 inflammasome by binding with Caspase-1 precursor and ASC." (PMID 38601463, 2024). "The NIHSS score, the mRS score after 90 days and the levels of NLRP1, CRP, TNF-α IL-6 and IL-1β of ischemic stroke patients in the ASITN/SIR grade 0 to 2 group were remarkably elevated than the ischemic stroke patients in ASITN/SIR grade 3 to 4 group." (PMID 37000063, 2023). "His most cited paper in this field is a 2013 article published in Cell death & disease that elucidates the inhibition of NLRP1 and NLRP3 inflammasome‐mediated neuronal death in ischemic stroke by intravenous immunoglobulin administration." (PMID 37088947, 2023). "The NIHSS score, infarct volume and the levels of NLRP1, IL-6, TNF-α, and IL-1β of ischemic stroke patients in the mRS score ≥ 3 group were remarkably elevated than the ischemic stroke patients in the mRS score ≤ 2 group." (PMID 37000063, 2023). "The NIHSS score, infarct volume and the levels of NLRP1, IL-6, TNF-α, and IL-1β of ischemic stroke patients in the mRS score ≥ 3 group were remarkably elevated than the ischemic stroke patients in the mRS score ≤ 2 group (P < .05)." (PMID 37000063, 2023). "NF‐κB and MAPK signaling pathways promote nucleotide‐binding oligomerization domain (NOD)–like receptor (NLR) Pyrin domain containing 1 and 3 (NLRP1 and NLRP3) inflammasome activation in neurons following ischemic stroke." (PMID 34674376, 2022). "In conclusion, further clinical studies should be conducted that deepen the relationship between clinical signs and ischemic stroke symptomatology and the expression levels of NLRP3 inflammasomes, NLRP1, NLRP2, and NLRC4 in damaged brain tissue." (PMID 36297283, 2022). "It was worth noting that NLRP1 and NLRP3 inflammasomes were reported to be involved in ischemic stroke." (PMID 34646128, 2021). "Particularly, NLRP1 and NLRP3 inflammasome-mediated neuronal pyroptosis performed an increasingly crucial role in the course of ischemic stroke." (PMID 34646128, 2021). "In ischemic stroke, MAPK and NF-κB signaling pathways are key links in the expression and activation of NLRP1 and NLRP3 inflammatory corpuscles." (PMID 33424599, 2020). "Finally, we reviewed other inflammasomes such as NLRP1, NLRP2, and NLRC4, the functions of which need to be clarified in the context of pathogenetic mechanisms that aggravate the sequelae of ischemic stroke." (PMID 36297283, 2022). "In addition, we provide some information regarding the contribution of NLRP1, NLRP2, and NLRC4 inflammasomes to ischemic stroke pathogenesis, highlighting potential therapeutic strategies that require further study." (PMID 36297283, 2022). "In addition, the serum NLRP1 levels and ASITN/SIR grade could predict the prognosis of ischemic stroke patients." (PMID 37000063, 2023).
ischemic stroke (continued). "Furthermore, emerging evidence suggested that the elevated expression of NLRP1 and NLRP3 inflammasome proteins could be modulated by the NF-κB signaling pathway in ischemic stroke." (PMID 34646128, 2021). "However, there are no more clinical studies on the role of NLRP1 in patients with ischemic stroke." (PMID 37000063, 2023). "Recent studies showed that various inflammasomes, containing NLRP1, NLRP2, NLRP3, NLRP10, NLR family card domain containing 4 (NLRC4), and absent in melanoma 2(AIM2) 35-39, are activated in ischemic stroke." (PMID 32788872, 2020).
Obesity (20 papers, 2016 to 2026). Accumulation of substantial excess body fat. "Future studies should be focus on illustrating how NLRP1 balance the production of pro-inflammatory IL-1 β and anti-obesity IL-18." (PMID 40433411, 2025). "Mice deactivated for NLRP1 inflammasome were shown to spontaneously develop obesity due to the decreased IL-18 production and lipolysis." (PMID 38483771, 2024). "NLRP1 mainly affected the blood glucose by reducing IL-18 production, inducing obesity and glucose consumption in mice and leading to significant IR." (PMID 36993972, 2023). "NLRP1 is also an innate immune sensor, which produces IL-18 under metabolic stress and inhibits obesity and metabolic syndrome." (PMID 37214347, 2023). "In the opposite direction, NLRP1 inflammasome was described to prevent obesity and metabolic syndrome through IL18 production." (PMID 32012784, 2020). "Recently it was shown that the Nlrp1 inflammasome, through the maturation of IL-18 in the adipose tissue, regulates the development of obesity and metabolic syndrome resulting from a rich caloric diet in C57BL/6 mice, by promoting lipolysis." (PMID 31554824, 2019). "In summary, it is likely that the two inflammasome sensors, NLRP1 and NLRP3, exert opposite effects in obesity; NLRP1 cleavage of IL-18 acts to limit metabolic dysfunction, while NLRP3 activation of IL-1β is detrimental and promotes glucose intolerance." (PMID 29515457, 2018). "In adipose tissue, NLRP1 is an innate immune sensor that functions in the context of metabolic stress to produce IL-18, preventing obesity and diet-induced metabolic dysfunction." (PMID 29342149, 2018). "A recent literature showed that the activation of NLRP1 inflammasome and subsequent IL-18 production prevent obesity and metabolic syndrome, indicating that NLRP1/IL-18 axis prevents T2D and likely DN." (PMID 27706238, 2016). "This could be due to the favorable role of NLRP1 on IL-18 production, as IL-18 deletion has been found to link to obesity and insulin resistance." (PMID 40433411, 2025). "However, in obesity and insulin resistance, IL-18 appears to counteract cardiometabolic dysfunction via the NLRP1 inflammasome." (PMID 39940942, 2025). "Additionally, decreased (P < 0.05) mRNA levels of Nlrp1, Nlrp3 and Nlrp6 in the small intestinal tract obtained from rats with diet-induced obesity were found." (PMID 38315242, 2024). "Interestingly, mice lacking the three murine Nlrp1 alleles (or Il18) develop metabolic syndrome and spontaneous obesity strengthening the functional link between metabolism and Nlrp1 sensors." (PMID 33138274, 2020). "Given that both the NLRP3 and NLRP1 inflammasome produce mature caspase-1 to cleave IL-18 and IL-1β, how these opposing effects occur, and in which cellular compartments, to drive or limit obesity remain unanswered questions that will be important to resolve." (PMID 29515457, 2018). "Moreover, IL-18 Production is regulated by the NLRP1 Inflammasome in the context of metabolic stress, Preventing Obesity and Metabolic Syndrome42." (PMID 29884798, 2018). "Murphy at al. demonstrated that mice lacking NLRP1 develop spontaneous obesity and MetS, and activation of NLPR1 prevents obesity possibly through regulating IL-18 production." (PMID 40433411, 2025). "It was reported that mice lacking the NLRP1 inflammasome showed reduced VAT IL18 production and lipolysis, leading to obesity and metabolic syndrome." (PMID 36482059, 2022).
Arthritis (19 papers, 2017 to 2024). Inflammation of a joint. "This very rare inflammasomopathy is caused by autosomal dominant or recessive mutations in Nlrp1, and is characterized by diffuse skin dyskeratosis, recurrent fevers, autoinflammation, and arthritis." (PMID 37443800, 2023). "NLRP1-associated autoinflammation with arthritis and dyskeratosis (NAIAD) is an autosomal recessive autoinflammatory disease characterized by recurrent fever, arthritis, dyskeratosis, and autoimmunity." (PMID 34258050, 2021). "Concerning treatments for AiKDs due to NLRP1 mutations, the IL-1 receptor antagonist anakinra was reported to be effective in cases of NLRP1-associated autoinflammation with arthritis and dyskeratosis." (PMID 32153585, 2020). "NLRP1 mutations have been reported to increase systemic amounts of caspase-1 in patients with arthritis and dyskeratosis; our results are consistent with these findings." (PMID 32695183, 2020). "Recently, mutations in the NLRP1 gene were shown to cause a novel autoinflammatory disorder that the authors proposed to call NAIAD (NLRP1-associated autoinflammation with arthritis and dyskeratosis) which causes arthritis and dyskeratosis." (PMID 31795299, 2019). "Recently, a novel gain-of-function mutation in NLRP1 gene that predisposes to inflammasome activation has been associated with NLRP1-associated autoinflammation with arthritis and dyskeratosis autoinflammatory syndrome." (PMID 28191008, 2017). "Interestingly, IL-18 is also the main driver of NLRP1-associated autoinflammation with arthritis and dyskeratosis." (PMID 37443800, 2023). "NLRP1 hyperactivity has been reported to cause inherited autoinflammatory diseases including familial keratosis lichenoides chronica and NLRP1-associated autoinflammation with arthritis and dyskeratosis." (PMID 35784371, 2022). "The NLRP1-associated autoinflammation with arthritis and dyskeratosis syndrome (NAIAD) is a novel monogenic autoinflammatory disease characterized by skin lesions (follicular hyperkeratosis), arthritis, recurrent fever of 3–4 days, and elevated acute phase reactants." (PMID 36253853, 2022). "NLRP1-associated autoinflammation with arthritis and dyskeratosis (NAIAD) was known to be associated with NLRP1 mutations." (PMID 35774778, 2022). "The NLRP1 rs2670660 SNP, especially when combined with the NLRP1 variant rs12150220, confers an increased risk of SLE and developing nephritis, arthritis and rash." (PMID 35457026, 2022). "The authors suggested that the P2X4 inhibitor attenuated the severity of arthritis in mice due to inhibition of the NLRP1 inflammasome." (PMID 33897694, 2021). "Treatment of CIA mice with BVT-2733, a selective inhibitor of 11β-hydroxysteroid dehydrogenase 1, attenuated arthritis severity by inhibition of the NF-κB and NLRP1 inflammasome signaling pathways." (PMID 31795299, 2019). "In a mouse model of arthritis, P2X4 inhibition led to a decrease in caspase-1, ASC, and NLRP1 and consequently a decrease in IL-1β production." (PMID 33897694, 2021).
breast carcinoma (17 papers, 2017 to 2025). "NLRP1 protein was indicated to be overexpressed in all human breast cancer subtypes, and a significant association between increased NLRP1 levels and lymph node metastasis was demonstrated." (PMID 38990306, 2024). "In melanoma, for example, NLRP1 was found to contribute to acquired drug resistance, and in breast cancer, was overexpressed in primary tissues and associated with lymph node metastasis." (PMID 34429144, 2021). "The study demonstrated that NLRP1 overexpression augmented breast cancer cell proliferation, migration, and invasion." (PMID 40237399, 2025). "A prior investigation in breast cancer revealed a significant positive correlation between the transcriptional level of NLRP1 and Ki‐67 levels, TNM stage, and lymph node metastasis." (PMID 40237399, 2025). "The overexpression of NLRP1 and increased levels of IL-1β in the tumor microenvironment have been emphasized to promote breast cancer malignity, progression, and migration." (PMID 38990306, 2024). "In that study, researchers evaluated the correlation between the expression of NLRP1 and various pathological characteristics of breast cancer patients." (PMID 38990306, 2024). "NLRP1 is predominantly overexpressed in breast cancer tissue, and the evaluated activation of NLRP1 inflammasome is associated with tumor growth, angiogenesis, and metastasis." (PMID 38990306, 2024). "When other breast cancer cell lines were examined, it was observed that SK-BR-3 cells expressed NLRP1 protein in almost similar amounts as healthy breast epithelial cells." (PMID 38990306, 2024). "In particular, the contribution of the NLRP1 inflammasome pathway to the development and progression of breast cancer is noteworthy." (PMID 38990306, 2024). "High expression levels of NLRP1 have also been found in human breast cancer mcf-7 cells and breast cancer tissues, and were correlated with lymph node metastasis, tumor lymph node metastasis stage and Ki-67 levels." (PMID 37497237, 2023). "In nude mouse transplantation models of breast cancer, overexpression of NLRP1 was found to promote breast cancer migration, invasion and growth by inducing epithelial-mesenchymal transformation." (PMID 37497237, 2023). "It has been proposed that NLRP1 inflammasomes promotes proliferation, migration and invasion of the breast cancer cell line MCF-7 compared to normal breast tissue." (PMID 37020871, 2023). "IL-1β, IL-18 and ASC, the pivotal elements of the inflammatory signaling pathway, are upregulated in breast cancer cells, but the specific cancer-promoting mechanism of NLRP1 inflammasomes needs to be further verified." (PMID 37020871, 2023). "For example, NLRP1, one member of our PR model and the core inflammasome in pyroptosis, was widely expressed in 83% of primary breast cancer (BC) tissue." (PMID 35000541, 2022). "Both pyroptosis-related inflammasomes including NLRP1, NLRP3, NLRC4, AIM2, and the following inflammatory cytokines IL-1β and IL-18 are associated with the immune system in breast cancer." (PMID 36119049, 2022). "Increased expression of NLRP1 occurs in breast cancer, and its transfection into cell lines promotes proliferation." (PMID 31923221, 2020). "High levels of NLRP1 were associated with clinic-pathological features including lymph node metastasis, TNM stage, and Ki-67 level in breast cancer patients." (PMID 29214170, 2017). "In this study, we overexpressed NLRP1 in human breast cancer MCF-7 cell and established xenograft tumor nude mice model and then observed that this protein promotes breast tumor migration, invasion, and growth." (PMID 29214170, 2017). "Overexpression of NLRP1 in the breast cancer cell line MCF-7 promotes proliferation, migration, invasion, and tumorigenicity in nude mice." (PMID 29214170, 2017). "In breast cancer tissues, expression levels of NLRP1 are substantially upregulated." (PMID 38990306, 2024).
breast carcinoma (continued). "However, comprehensive studies investigating the role of NLRP1 activation in the antiproliferative effects of COX-2 inhibitors in breast cancer are limited." (PMID 38990306, 2024). "Moreover, elevated NLRP1 expression levels promote breast cancer cell proliferation, metastasis, and invasion." (PMID 36246601, 2022). "In mice, NLRP1 also promoted breast cancer proliferation, invasion, metastasis, and tumorigenicity." (PMID 34429144, 2021). "Furthermore, CASP8 (2%), NLRC4 (1%), NLRP3 (1%), NLRP2 (1%), PLCG1 (1%), NLRP1 (1%), NLRP7 (1%), SCAF11 (1%), GSDMC (1%), and NOD1 (1%) occurred somatic mutations as well as most of them had high frequencies of CNV in breast cancer." (PMID 34589498, 2021). "Moreover, NLRP1 promotes breast cancer cell proliferation, migration, and invasion by inducing the epithelial–mesenchymal transition (EMT)." (PMID 32397236, 2020). "The aim of this study was to examine the expression and function of NLRP1 in breast cancer." (PMID 29214170, 2017). "We found that NLRP1 transfection promoted breast cancer cell line MCF-7 proliferation, migration, and invasion by possibly activating EMT and inflammasomes, mesenchymal markers vimentin, C-myc, MMP-9, and snail were upregulated, and then epithelial marker E-cadherin was downregulated." (PMID 29214170, 2017). "Herein, we report that NLRP1 is highly expressed in breast cancer tissue." (PMID 29214170, 2017). "We found that NLRP1 was widely expressed in 83% (60/72) of primary breast cancer tissue." (PMID 29214170, 2017). "After demonstrating the expression of NLRP1 protein in three different breast cancer cells and highlighting its dramatic upregulation in MDA-MB-231 cells, we investigated whether COX-2 enzyme inhibitors affect the expression of NLRP1 inflammasomal components in MDA-MB-231 cells." (PMID 38990306, 2024). "Besides NLRP3, COX-2 inhibitors may have anticancer effects by inhibiting the inflammatory activation of NLRP1, which is predominantly highly expressed in breast cancer tissue." (PMID 38990306, 2024). "A previous study discovered that NLRP1, NLRP3, NLRC4, and AIM2 inflammasome complex proteins had pro- or antitumoral properties, especially in breast cancer." (PMID 36437954, 2022). "In particular, via controlling innate and adaptive immunity as well as tumor growth, NLRP1, NLRP3, NLRC4, and AIM2 have an effect on how breast cancer develops." (PMID 36119049, 2022). "Further study is also needed to elucidate the mechanisms of NLRP1 and EMT in breast cancer, such as Wnt/β-catenin signaling." (PMID 29214170, 2017). "This study is the first time to describe the detailed function in solid tumor and uncover the interaction between NLRP1 and EMT in breast cancer." (PMID 29214170, 2017). "However, the role of NLRP1 in breast cancer pathogenesis remains unclear." (PMID 29214170, 2017). "Recent studies indicated that NLRP1 expression was higher in primary breast cancer tissue than in adjacent noncancerous tissue and was associated with lymph node metastasis, tumor-node-metastasis (TNM) stage, and Ki-67." (PMID 36437954, 2022). "These researches indicate that the high expression and activation of inflammasomes NLRP3, NLRP1, and NLRC4 may promote breast cancer progression including growth, metastasis, and invasion." (PMID 36119049, 2022). "We previously demonstrated that the factors secreted by hUCMSCs induced pyroptosis in the breast cancer cell line MCF7.Furthermore, RNA sequencing studies revealed a significant increase in the expression of pyroptosis-related genes CASP4 and NLRP1 in pyroptotic MCF7cells." (PMID 32695183, 2020).
breast carcinoma (continued). "NLRP1 expression is higher in primary breast cancer tissue than in adjacent noncancerous tissue and is associated with lymph node metastasis, tumor-node-metastasis (TNM) stage, and Ki-67 levels." (PMID 32397236, 2020). "But, in this study, we have not yet completed the detailed mechanism that NLRP1 promotes the malignant processes of breast cancer." (PMID 29214170, 2017). "But the expression and functional role of NLRP1 in primary breast cancer has not been reported previously." (PMID 29214170, 2017). "NLRP1 expression level was higher in primary breast cancer tissue than in adjacent noncancerous tissue (p < 0.001) and NLRP1 expression was associated with lymph node metastasis (p = 0.003), TNM stage (p = 0.003), and Ki-67 levels (p < 0.001)." (PMID 29214170, 2017). "Yuxian Wei discovered that primary breast cancer tissue had higher levels of NLRP1 expression compared to neighboring non-cancerous tissue and there was a link between NLRP1 expression and clinical indexes such as Ki-67 levels, TNM stage, and lymph node metastasis." (PMID 36119049, 2022).